INS (insulin)
Diseases named in the same sentence as INS in open-access papers (continued):
Sharing a sentence is not in itself a finding about the gene and the disease.
Insulin resistance (continued). "Metformin addresses insulin resistance primarily in the liver and skeletal muscle and mainly reverses hyperglycaemia through a reduction in hepatic glucose production, while the thiazolidinediones increase whole-body insulin-mediated glucose disposal to a greater extent than metformin." (PMID 20089006, 2010). "It has been suggested that since triglycerides are related to insulin, this lipid could indicate an aspect of extensive metabolic disorder including insulin resistance, and that this could be a reason as to why triglycerides are the lipids which show the most consistent association to birth weight." (PMID 20712860, 2010). "Furthermore, since hyperglycemia is also observed during BD as a result of stress-related peripheral insulin resistance, insulin substitution may be needed to achieve normoglycemia." (PMID 21087498, 2010). "Furthermore, several studies suggest that iNOS induction is involved in cytokine-induced insulin resistance, given that increased iNOS expression is related to an impaired insulin-stimulated glucose uptake revealing a profound involvement of iNOS in both immunologic and metabolic systems." (PMID 20532036, 2010). "In this study, C57BL/6 mice were fed with high-fat diet (HFD) to establish insulin resistance for investigating the effects of apocynin on the expression of inflammatory factors in blood, liver, and adipose tissue, and then evaluating the improvement of insulin sensitivity with apocynin treatment." (PMID 21403905, 2010). "Therefore the synergistic effects of PPARγ and the HO system in improving insulin sensitivity and glucose metabolism may be a novel approach to combat insulin resistance and related cardiometabolic complications." (PMID 20508722, 2010). "Furthermore, a murine model of hyperinsulinaemia and insulin resistance is associated with increased TIMP-1 and -2 levels, suggesting that insulin homeostasis may affect extracellular matrix metabolism via TIMP-mediated processes." (PMID 20565712, 2010). "Moreover, we have indentified potential gene targets in energy metabolic pathways and signal transducers that may contribute to obesity-related insulin resistance as well as calorie restriction and alcohol-induced insulin sensitivity." (PMID 20307313, 2010). "While we know a lot about the mechanisms by which adiposity leads to insulin resistance and how exercise increases insulin sensitivity, it hasn't been yet reported about the exercise-induced changes in chemerin concentrations, which may provide a link between obesity and insulin resistance." (PMID 22375203, 2010). "In addition, the abuse of GH by healthy subjects seeking its anabolic or lipolytic effects may impair glucose metabolism and increase insulin levels, and therefore enhance the oxidation of lipid substrates and result in insulin resistance." (PMID 21087523, 2010). "In patients with obesity, metabolic syndrome and type 2 diabetes, characterized by target-tissue resistance to insulin, adipocyte-derived factors (adipokines) have been identified which signal to the brain, adipose tissue, liver, muscle, and the immune system, and thus influence insulin resistance." (PMID 19545363, 2009). "Recuperated animals expressed decreased levels of many insulin signalling proteins including PI3 kinase subunits p85α (P = 0.018), p110β (P = 0.048) and protein kinase C zeta (P = 0.006) which may predispose these animals to insulin resistance." (PMID 19308256, 2009). "Hence, parental insulin sensitivity could well serve as a representation of the offspring's future insulin resistance state." (PMID 20062558, 2009). "There is debate regarding whether obesity or insulin resistance (IR, i.e. the condition in which normal amounts of insulin are inadequate to produce a normal insulin response) are the cause of the metabolic syndrome or if they are consequences of a more far-reaching metabolic derangement." (PMID 19828068, 2009).
Insulin resistance (continued). "We examined the expression of the novel isoform of the LAR transcript in an established model of developmentally programmed adult insulin resistance in order to identify whether this specific transcript may play a role in the development of the insulin resistant phenotype." (PMID 19356234, 2009). "The data demonstrated an interaction between testosterone and insulin on phosphorylation of intracellular signaling proteins, and suggests a link between a hyperandrogenic, hyperinsulinemic environment and the development of insulin resistance involving serine phosphorylation of IRS-1 Ser636/639." (PMID 19169352, 2009). "Finally, recent studies suggest that increased oxidative stress in adipose tissue is a contributing factor to insulin resistance in obesity and that insulin sensitization by PPARγ agonists is mediated, at least in part, by suppressing oxidative stress in adipose tissue." (PMID 19390629, 2009). "Finally we could also hypothesize that increased insulin secretion in response to central IL infusion could, at least in part, be responsible for increased hepatic insulin resistance." (PMID 19680547, 2009). "Insulin resistance has been linked to the accumulation of intramyocellular lipids in skeletal muscle of diabetic patients in relation with the lipogenic transcription factor SREBP-1c which mediates insulin's actions on hepatic and skeletal muscle gene expression in humans and rodents." (PMID 20041157, 2009). "The insulin sensitizing drugs have induced in most of the studies, the improvement of the endocrineand reproductive parameters simultaneously with the amelioration of the insulin resistance and hyperinsulinemia, suggesting this to be the mainbeneficial mechanism in PCOS." (PMID 20108521, 2008). "Considering the metabolic syndrome as accompanied by insulin resistance with prolonged hyperinsulinemia, such a mitochondrial dysfunction appears to be analogue to the persistent inhibitory effects on mitochondrial respiration demonstrated by the presented data at intermediate insulin concentration." (PMID 18335029, 2008). "Decreased muscle glucose uptake in response to insulin (i.e., decreased insulin action, otherwise known as “insulin resistance”) has been demonstrated in patients with type-1 diabetes and this might contribute to the development and maintenance of their poor glycaemic control." (PMID 18852875, 2008). "While obesity has been strongly associated with increased insulin resistance, our data suggests that insulin secretory variants confer a greater T2D risk in non-obese individuals while insulin sensitivity variants more significantly modulate T2D risk in obese subjects." (PMID 18498634, 2008). "Considering that insulin sensitivity and decreased insulin response are major pathophysiological components of obesity and type 2 diabetes, the present study was undertaken in order to evaluate the relationship of body composition to insulin resistance among adolescents." (PMID 18553029, 2008). "Further research is required to clarify how these insulin resistance-related factors, as they come into play as confounding factors, may behave after initiation of insulin therapy to elucidate the relationship between exogenous insulin and adiponectin." (PMID 18507868, 2008). "Resistin might contribute to peripheral insulin sensitivity and insulin resistance." (PMID 21876654, 2008). "Therefore, we investigated whether FAK contributes to insulin-induced actin remodeling and harbor Glut-4 for glucose transport and whether downregulation of FAK affects the remodeling and causes insulin resistance." (PMID 18771597, 2008). "Therefore the ERα mediated increase of insulin content by BPA in pancreatic β-cells may contribute to the BPA-provoked insulin resistance demonstrated in vivo." (PMID 18446233, 2008). "However, the usefulness of insulin levels ap as markers for insulin resistance needs further study." (PMID 18687108, 2008).
Insulin resistance (continued). "These elevated levels of free fatty acids may lead to an increased flux to the liver and muscle, leading to the formation of lipid moieties such as diacylglycerol and ceramide, which have been shown to alter insulin signaling and thus lead to insulin resistance." (PMID 17593968, 2007). "Thus, insulin resistance is essential for survival, but too much can result in a feed-forward "feed-inflammatory" response: the 'thrifty' response out of control – as it also suppresses the hypothalamic satiety effects of insulin and leptin." (PMID 17531095, 2007). "Insulin suppresses Pdk4 expression in skeletal muscle and, according to a recent study by Kim and coworkers, this effect is impaired in insulin resistance, suggesting that insulin resistance may indeed induce Pdk4 expression." (PMID 17949489, 2007). "The development of insulin resistance in mammals with elevated expression of an antioxidant enzyme and suggest that increased GPx-1 activity may interfere with insulin function by overquenching intracellular reactive oxygen species required for insulin sensitizing." (PMID 17825092, 2007). "Results from the current study and studies of insulin and insulin resistance suggest that pancreatic carcinogenesis may be influenced by circulating insulin levels, whereas plasma levels of IGF-I, IGF-II, and IGFBP-3 may have little effect on the long-term risk for this malignancy." (PMID 17533398, 2007). "Second, BMI, waist and insulin may only imperfectly represent insulin resistance and the effect of such markers on the relationship between IGR and major CVD risk factors might have been larger, had we used better indicators of insulin resistance." (PMID 17958881, 2007). "Additionally, treatment with metformin, an oral hypoglycemic agent that leads to decreases in peripheral insulin resistance and pancreatic insulin production, may prevent the development of malignant lesions." (PMID 17533398, 2007). "Our data suggest that the presence or formation of modified/oxidized/aggregated LDL in insulin-resistant patients, who have increased blood insulin and glucose, may exacerbate existing insulin resistance and contribute to the development and progression of type 2 diabetes." (PMID 16787541, 2006). "The interpretation of in-vivo metabolic studies is further complicated because hypoxia inhibits insulin secretion through decreased β-cell ATP production but may also reduce insulin receptor tyrosine kinase activity leading to insulin resistance and hyperinsulinaemia." (PMID 17078884, 2006). "Improving insulin resistance with exercise, low-calorie diet and insulin-lowering drugs such as metformin, troglitazone and acarbose decrease insulin levels, correct the endocrine abnormalities induced by obesity and insulin resistance which may improve the outcome of infertility treatment." (PMID 16202169, 2005). "In addition to these measures of glycemia, this study also used the HOMA-IR index, a measure of insulin resistance derived from fasting levels of glucose and insulin and a physiologically-based model, which is an effective, easily-derived surrogate for the more complex euglycemic clamp." (PMID 15892894, 2005). "Insulin resistance, both in the liver calculated with HOMA-IR and of whole-body using Matsuda insulin sensitivity index, was unaffected by ETI." (PMID 41489009, 2026). "Metformin has been reported to improve glucose tolerance, ameliorate insulin resistance, and reduce obesity by increasing TUDCA levels, while GUDCA has also been shown to improve insulin sensitivity in diabetic populations." (PMID 41514462, 2026). "Ras hyperactivation promotes insulin resistance and inflammation via MAPK/PI3K pathways, whereas RalA supports GLUT4 translocation and insulin granule exocytosis." (PMID 42075902, 2026). "Fasting insulin levels were also elevated in this group, resulting in a significantly higher HOMA-IR index, indicating greater insulin resistance." (PMID 41595473, 2026).
Insulin resistance (continued). "Insulin resistance was estimated using HOMA-IR, and the leptin-to-adiponectin ratio (LAR)-a marker of fasting and postprandial insulin sensitivity-was calculated." (PMID 41618682, 2026). "Moreover, the greater insulin levels observed in aged mice may indicate insulin resistance." (PMID 41543803, 2026). "To investigate the role of macrophage Gpx4 in obesity related insulin resistance, we performed glucose tolerance tests (GTT) and insulin tolerance tests (ITT) in chow‐ and HFD‐fed Gpx4fl/fl and Gpx4Mac‐KO mice." (PMID 41524084, 2026). "Glycaemia, insulin, HOMA-IR, Metabolic Score for Insulin Resistance (METS-IR), liver enzymes and hepatic steatosis and fibrosis indices remained stable." (PMID 41603415, 2026). "Excessive accumulation of long-chain fatty acids (LCFAs) in cardiomyocytes leads to cardiac lipid-induced insulin resistance (CLIR), impairing insulin signaling and glucose uptake." (PMID 41886090, 2026). "Fasting insulin (FINS), fasting C-peptide (FCP), homeostasis model assessment of β-cell function (HOMA-β), and homeostasis model assessment of insulin resistance (HOMA-IR) also showed significant intergroup differences (all P < 0.001)." (PMID 42318225, 2026). "Results: miR-122 was found to negatively regulate genes involved in lipid metabolism, insulin signaling, and inflammatory pathways, including PPARGC1A, PPARA, LPL, TLR4, and HMGCR, contributing to insulin resistance and liver dysfunction." (PMID 41595656, 2026). "Flavonoids such as galangin, improve insulin-dependent function by translocating GLUT4 transporters and modulating PI3K/Akt distribution, which helps reduce insulin resistance." (PMID 41599361, 2026). "A daily insulin resistance index (IRI) was computed from glucose and insulin data and corrected for steroid exposure." (PMID 41736099, 2026). "This is due to insulin resistance in individuals with T2DM and obesity, which elevates blood levels of both insulin and glucose." (PMID 41607999, 2026). "Restricted cubic spline (RCS) curves were utilized to explore potential nonlinear relationships, and mediation analysis was conducted to investigate the mediating role of insulin resistance in the effects of DAL on fasting blood glucose and insulin." (PMID 41952767, 2026). "Moreover, mineralocorticoid receptor blockade in adipose tissue reduces obesity‐related insulin resistance by decreasing oxidative stress and inflammatory macrophage infiltration, yet these local improvements may be masked when evaluating systemic insulin sensitivity using ITT or GTT." (PMID 41042601, 2026). "Glucose dysregulation was assessed using the homeostasis model assessment of insulin resistance (HOMA‐IR), fasting plasma glucose (FPG), impaired fasting glucose (IFG), fasting plasma insulin (FPI), and abnormal glucose regulation (AGR)." (PMID 40963334, 2026). "These miRNAs influence critical insulin signalling genes (INSR, PIK3R1, AKT2) and steroidogenic regulators (STAR, CYP19A1), hence propagating insulin resistance and steroidogenic dysregulation to adjacent granulosa cells." (PMID 41010046, 2025). "Group-based comparisons of circulating growth factors and insulin resistance markers revealed statistically significant differences in IGF-2 (p < 0.001), HOMA-IR (p < 0.001), insulin (p = 0.0025), and glucose concentrations (p < 0.001)." (PMID 40943286, 2025). "Therefore, longitudinal studies with wider coverage and larger sample size involving additional biomarkers that assess both fasting and postprandial insulin and glucose indices may be necessary to better understand the promoting factors of insulin resistance in our context." (PMID 40273152, 2025). "Vitamin D (VD) is thought to play a crucial role in the onset of insulin resistance and the pathogenesis of T2DM by influencing insulin sensitivity and β-cell function." (PMID 40313432, 2025).
Insulin resistance (continued). "Regarding glucose homeostasis parameters and insulin resistance parameters at birth, the GDM group had significantly higher values than the control group (HgbA1c (p < 0.0001), insulin (p = 0.003), and C-peptide (p = 0.008))." (PMID 40004118, 2025). "Insulin resistance, a characteristic pathophysiological defect in most T2DM patients, directly disrupts the insulin signaling pathway." (PMID 40909136, 2025). "IPGTT, plasma insulin levels and IPITT results indicated impaired glucose tolerance and insulin resistance in HFD-fed groups, with aged mice showing more pronounced metabolic dysfunction." (PMID 40585885, 2025). "Regarding glucose metabolism, WMSZY significantly improved blood sugar, insulin levels, and HOMA-IR, and OGTT results further confirmed its effect on enhancing insulin resistance (IR)." (PMID 41194880, 2025). "HOMA-IR and QUICKI, which are based on fasting glucose and insulin levels, are simple and widely used indices of insulin resistance, but they reflect basal, not dynamic, states and may be less reliable in populations with extreme insulin resistance or decreased β-cell function." (PMID 39857881, 2025). "The changes in myostatin levels after the intervention were positively correlated with the changes in insulin levels and also positively correlated with the changes in the HOMA-IR index, a marker of insulin resistance." (PMID 40806137, 2025). "On the contrary, lowering insulin below fasting levels with somatostatin reduced BGM in metabolically healthy individuals but significantly less in insulin resistance." (PMID 39185744, 2025). "Serum insulin levels were markedly increased in the CON group, further indicating insulin resistance." (PMID 40508039, 2025). "GGPP also activates KRAS/MEK/ERK signaling, which inhibits the insulin signaling pathway PI3K-AKT, leading to insulin resistance." (PMID 40412522, 2025). "Subgroup analyses based on study design, health status, intervention duration, and dosage also failed to reveal any improvement in fasting blood glucose (FBG), homeostatic model assessment of insulin resistance (HOMA-IR), or insulin (INS)." (PMID 41586243, 2025). "Quantitative Insulin Sensitivity Check Index (QUICKI), Homeostatic Model Assessment for Insulin Resistance (HOMA‐IR), atherogenic, thrombogenic, and lipophilic indices were calculated." (PMID 40041714, 2025). "In experiments with SOCS2-deficient mice, a high-fat diet resulted in impaired glucose tolerance and insulin resistance, while SOCS2 overexpression improved glucose tolerance and insulin sensitivity." (PMID 40362828, 2025). "On top of that, vaspin prolonged the insulin half-time by inhibiting KLK7, which naturally helps mitigate insulin resistance." (PMID 41463050, 2025). "Group A showed the least insulin resistance (HOMA-IR = 0.84, QUICKI = 0.38, insulin = 3.95 μIU/mL), suggesting a milder metabolic profile." (PMID 41220482, 2025). "The Homeostasis Model Assessment of Insulin Resistance (HOMA-IR; fasting glucose [mmol/L]×fasting insulin [μU/ml]/22.5) is regarded as an acceptable method for evaluating IR." (PMID 40512995, 2025). "This anti-inflammatory context is critical for restoring insulin signaling, as it prevents inhibitory phosphorylation in IRS-1 serine residues, a central mechanism in the pathogenesis of insulin resistance." (PMID 41471698, 2025). "The skeletal muscle-tissue-specific insulin response and impairment in insulin-resistant mice and humans emphasize the clinical relevance of REPS1 as a potential therapeutic target for diseases characterized with insulin resistance, such as T2D." (PMID 40482643, 2025). "Outcome measures included FBG, insulin levels, or Homeostatic Model Assessment for Insulin Resistance (HOMA-IR, an index used to estimate insulin resistance based on FBG and insulin levels, with higher values indicating increased insulin resistance)." (PMID 40471419, 2025).